ADAM17 (ADAM metallopeptidase domain 17)
Diseases named in the same sentence as ADAM17 in open-access papers (continued):
Sharing a sentence is not in itself a finding about the gene and the disease.
tumor (continued). "Chemotherapy-induced apoptosis elevates transcription and activates ADAM17, a principal metalloproteinase that orchestrates shedding and pro-survival responses in cancer cells through the release of factors that enhance tumor growth via autocrine and/or paracrine signaling." (PMID 26993100, 2016). "Based on the results from the LPS+IFNγ studies, we hypothesized that ADAM17 regulates Cox-2 expression in macrophages in response to tumor cell-derived factors as well." (PMID 27738494, 2016). "According to their report, an ADAM17-specific inhibitor not only rescues FcγRIIIA shedding stimulated by tumor targets but also improves NK cell degranulation as well as IFNγ production in the presence of tumor-specific mAb." (PMID 26284063, 2015). "ADAM17 overexpression has been demonstrated in numerous human tumors and several well-designed studies have shown correlations between the levels of ADAM17 expression and tumor progression." (PMID 26176220, 2015). "However, ADAM17 can be upregulated on some tumor cells and on T lymphocytes by stimulation with TPA and Ionomycin." (PMID 24130797, 2013). "In parallel, we addressed the expression of ADAM17 on the same set of tumor cells and T cell lines." (PMID 24130797, 2013). "We investigated the constitutive and inducible surface expression of ADAM10 and ADAM17 on selected tumor cells of different origin and on resting and activated T lymphocytes in a time-frame of three hours without or with stimulation by phorbol ester and calcium ionophore." (PMID 24130797, 2013). "When we addressed stimulation-dependent alterations in ADAM17 surface levels, we noted a significant increase in ADAM17 after incubation with phorbol ester and Ionomycin on individual tumor cell lines (i.e. the fibrosarcoma line HT1080) and some tested T cell populations." (PMID 24130797, 2013). "Thus, the resulting cell lines meet the basic criteria for a proper model to study the role of ADAM17 in tumor progression." (PMID 23251384, 2012). "Well-designed experimental approaches confirmed the importance of ADAM17 in tumor progression." (PMID 23251384, 2012). "Does ADAM17 contribute to MC38CEA tumor development through NRG-1 shedding?" (PMID 23251384, 2012). "The question arose whether ADAM17-silencing inhibits tumor growth via inhibiting angiogenesis or, alternatively, whether slower growth of tumors delays occurrence of hypoxia and initiation of angiogenesis." (PMID 23251384, 2012). "Another possible explanation for the difference between the ADAM17 substrates is that TNF-α shedding might occur deeper within the tumour mass (where antibody penetration may be limiting) than the shedding of the EGFR ligands." (PMID 22792380, 2012). "However, some studies unambiguously documented increased ADAM17 expression within tumor cells and its correlation with tumor progression." (PMID 23251384, 2012). "The identification of the ADAM17 substrate present in MC38CEA that may influence anti-tumor immune response will be a priority for the future research." (PMID 23251384, 2012). "If the D1(A12) was unable to inhibit TNF-α shedding by ADAM17 deep in the tumour this pharmacokinetic feature could also explain the discrepancy between the in vitro and in vivo studies, as the cells in vitro would all be exposed to the antibody." (PMID 22792380, 2012). "We hypothesized that the immune system that contributes to tumor microenvironment is at least partially responsible for the inhibition of the growth of ADAM17-silenced tumors." (PMID 23251384, 2012). "Therefore, the aim of our work is to elucidate novel pathways via which ADAM17 promotes tumor development." (PMID 23251384, 2012). "However, D1(A12) did show clear pharmacodynamic effects in the mice, with significant inhibition of shedding from tumour of ADAM17 substrates TNFR1-α, AREG, and TGF-α (4–15-fold reductions, p<0.0001 for all three)." (PMID 22792380, 2012).
tumor (continued). "Our results suggest that NRG-1 released from MC38CEA by ADAM17 activates ErbB2 phosphorylation, which could play a role in an autocrine tumor promoting network." (PMID 23251384, 2012). "MDSCs cleave L-selectin from T cells because they constitutively express ADAM17 at their cell surface and, as a result, T cells cannot traffic to tumor draining lymph nodes, where they normally would have access to tumor antigens and consequently can not be activated." (PMID 22481970, 2012). "In this study, we investigated whether Sp1 transcription factor induces ADAM17 and/or contributes to tumor cell invasiveness in hypoxia." (PMID 19772640, 2009). "Knowing that ADAM17 contributes to the invasiveness of tumor cells and that Sp1 binds to its promoter region, it is possible that Sp1 transcription factor may be a new target for anti-invasive therapies." (PMID 19772640, 2009). "Therefore, in the current study, we decided to evaluate whether there is a correlation between SIR indices and the concentration of ADAM10 and ADAM17 in tumor tissue and surgical margin." (PMID 39940871, 2025). "Consequently, ADAM17 levels may serve as a biomarker for monitoring tumor progression and assessing chemotherapy sensitivity in patients." (PMID 40757000, 2025). "However, CD16a undergoes cleavage by ADAM17 that dampens its anti-tumor immunity." (PMID 41219228, 2025). "Based on the exosomal ADAM17 levels in the serum of patients with tumors, exosomal ADAM17 expression was negatively correlated with VE-cadherin, p120, and E-cadherin levels at the tumor invasive front and positively correlated with the expression of tumor blood metastatic protein vimentin." (PMID 38413999, 2024). "Moreover, ADAM17 deletion in CD8+ T cells exhibited an enhanced anti-tumor activity." (PMID 38918390, 2024). "As ADAM17 maturation is decreased in multiple tissues of iTAP/Frmd8 KO mice, including the lung, and defects in its sheddase activity were observed in ex vivo and in in vivo experiments, we next evaluated the effect of iTAP/Frmd8 depletion on tumor growth and metastasis." (PMID 36720499, 2023). "Therefore, different molecules on the EV surface (including ALCAM and ADAM17) are involved in the interactions between tumor-derived EVs and recipient cells and the adhesive capacity of these molecules may be subjected to additional regulation by EV CD9." (PMID 35628559, 2022). "The overexpression of ADAM17 may enhance the migratory ability of GC cells and tumour growth." (PMID 35565436, 2022). "Herein, we summarized and updated multiple regulatory roles of ADAM17 as well as the development of ADAM17 inhibitors with a focus on the immunomodulatory role of ADAM17 in tumor development, which may provide reasonable insights for the prevention and treatment of cancer diseases." (PMID 36466812, 2022). "The hypomethylation of ADAM17 in PAAD tumor tissues appeared to be positively correlated with the higher expression shown in our previous report, implying that hypomethylation of the ADAM17 promotor may be responsible for its increased expression in PAAD tissues." (PMID 36558177, 2022). "In addition, ADAM17 protein is responsible for the activation of TNFα, initiating the signalling pathway associated with the EGF receptor for which it is a ligand, leading to tumour cell proliferation." (PMID 35565436, 2022). "Disintegrin and Metalloprotease 17 (ADAM17) was identified as a novel important regulator of necroptosis whose activity could significantly affect the role of TNFR1-dependent tumor cell induction of endothelial cell death, tumor cell extravasation, and subsequent metastatic seeding." (PMID 35958626, 2022). "Therefore, blocking ADAM17-mediated hydrolytic activity to inhibit MICA shedding may be one of the ways to improve NK cell killing of tumor cells." (PMID 36466812, 2022).
tumor (continued). "A key regulator in tumor metabolism, promotion of uncontrolled tumor cell growth, and autogenously cell interaction by releasing growth factors and overexpressing corresponding receptors is the metalloprotease ADAM17, of which is reported to cleave a substantial number of substrates." (PMID 36497350, 2022). "We speculate that ADAM17 is likely to be a novel target for tumor immunotherapy." (PMID 35720350, 2022). "It is speculated that endothelial ADAM17 may help tumor metastasis." (PMID 36466812, 2022). "Interestingly, ADAM17 is also present in platelets and is involved in tumor immune escape." (PMID 36466812, 2022). "Hence, inhibition of ADAM17 on tumor cells and NK cells could strongly enhance anti-tumor immunity alone and as part of combined treatment modalities with different targeting agents and immunogenic cell death inducers." (PMID 34055644, 2021). "Blocking ADAM17 may have additional anti-tumor effects as well." (PMID 34367174, 2021). "Our FACS-based quantification of tumor cell associated surface VEGF levels in response to irradiation alone and in combination with MEDI3622 thereby do not mechanistically dissect these processes but support and complement our new data on ADAM17-dependent irradiation-induced release of VEGF." (PMID 36860547, 2021). "Therefore, the inhibition of ADAM17 might affect multiple tumor-relevant molecules and corresponding pathways." (PMID 34070094, 2021). "Moreover, ADAM17 expression was high in both tumor regions and cell types." (PMID 33672843, 2021). "Therefore, we hypothesize that increased ADAM17 released into the bloodstream is rather a surrogate for tumor progression in early-stage disease than a surrogate for increased tumor burden of advanced disease, pointing to the complex regulation of ADAM17." (PMID 34771725, 2021). "Furthermore, IR-induced and VEGF-mediated intercellular communication required release of VEGF in an ADAM17-dependent manner and could be abrogated through inhibition of ADAM17 in the attracting tumor cells." (PMID 36860547, 2021). "Thus, it is tempting to speculate that at least one of the roles of PP2A‐B56 as a tumor suppressor can be explained by its ability to restrict ADAM17‐mediated EGFR signaling." (PMID 32400009, 2020). "Next, we investigated whether the binding of PP2A‐B56 to ADAM17 influences in vivo tumor growth." (PMID 32400009, 2020). "The overexpression of ADAM17 may enhance the ability of migration of GC cells and tumor growth." (PMID 32610677, 2020). "Release of sIL-6R by ADAM17 to promote IL-6 trans-signaling can be facilitated by tumor cells and macrophages, whereas ADAM17 on myeloid cells is speculated to release EGF-R ligands and activate EGF-R signaling in an autocrine manner, as well as on macrophages." (PMID 33143292, 2020). "In addition, inhibition of ADAM17 can reduce the invasion of tumor cells induced by hypoxia." (PMID 32610677, 2020). "Thus, miR‐449b‐3p mediated NPC tumor inhibition by downregulating ADAM17." (PMID 31433128, 2019). "Furthermore, after the transplantation of ADAM17 overexpressing cells, an increase in tumor cell proliferation as well as in tumor size could be detected." (PMID 30917608, 2019). "In addition, ADAM17 protein is responsible for the activation of TNFα, initiating the signaling pathway associated with the EGF receptor for which it is a ligand, leading to tumor cell proliferation." (PMID 31565100, 2019). "Taken together, whereas the known α-secretase enzymes, mainly ADAM10 and ADAM17 (TACE) and in some degree ADAM9, are involved in APP α-secretase cleavage, they are not APP-specific and cleave various substrates associated with inflammation, tumor formation, and progression." (PMID 29560732, 2018). "Based on our initial findings that ADAM17 regulates Cox-2 expression in response to inflammatory stimuli, further studies were performed to determine whether Cox-2 is induced in macrophages following exposure to tumor cell-derived factors." (PMID 27738494, 2016).
tumor (continued). "In this work we addressed the issue of whether ADAM17 may also promote tumor lymphangiogenesis." (PMID 26176220, 2015). "This suggests that ADAM17 may affect tumor angiogenesis and the invasive activity of tumor cells." (PMID 25351873, 2015). "It is possible that ADAM-17 in the tumor bearers could affect cleavage of SEMA7A." (PMID 24550834, 2014). "Thus, the D1(A12) specific ADAM17 inhibitor which showed modest antitumour effects in the IGROV1-Luc model may show more effective antitumour activity in tumours that are dependent on EGFR ligand signalling." (PMID 22792380, 2012). "Elevated ADAM8, ADAM9, ADAM12 and ADAM17 levels were observed in CRC tissues and correlated with more advanced tumor stage, while increased serum ADAM15 concentrations associated with the presence distant metastases." (PMID 41976350, 2026). "In vivo studies revealed that D1(A12), a cross-domain antibody that binds to both the M and D+C domains of ADAM17, was effective in reducing the tumour burden in mice with IGROV1-Luc tumours." (PMID 40427200, 2025). "ADAM17 is a key molecule that regulates EGFR ligand activation and inflammatory signaling, contributing to tumor–stromal communication." (PMID 41374933, 2025). "In CRC, ADAM17-mediated IL-6 trans-signalling and subsequent STAT3 activation drive tumour growth, as well as inflammation and immune evasion." (PMID 40427200, 2025). "Inhibition of iRhom1 and thereby blocking subsequent ADAM17‐mediated shedding of CD44, enhanced tumor uptake of CD44 directed chemotherapeutics and increased tumor clearance in multiple cancers in mice." (PMID 41015904, 2025). "Compared with the selective inhibitor of ADAM10 (GI254023X), the ADAM17 inhibitors JG26 and aderbasib effectively reduced the permeability and tumor cell adhesion induced by EMT-HCT116 exosomes." (PMID 38413999, 2024). "It is shown that suppressing cleavage of HER2 by INCB7839 (an ADAM10/ADAM17 inhibitor) decreases soluble HER2 ECD formation and also membrane p95 levels and subsequently renders tumor cells' response to treatment with trastuzumab." (PMID 38317965, 2024). "In particular, exosomal ADAM17 is highly expressed in metastatic cell lines, such as SW620 and Lovo, and is closely related to tumor metastasis." (PMID 38413999, 2024). "One example is enhancing miR-122’s tumor-suppressing action by targeting ADAM10, IGF1R, cdk G1, and ADAM17." (PMID 38915826, 2024). "CRISPR/Cas9 technology has been applied by Pomeroy and colleagues to knock out the ADAM17 cleavage sequence in PB-NK cells, which led to upregulation of IFN-γ production and ADCC in a PD-1 knockout combined in vitro study including tumor-targeting mAbs." (PMID 39339180, 2024). "In conclusion, we reveal an essential role of ADAM17-mediated ectodomain shedding of CD122 signaling in enhancing effector CD8+ T cell response and anti-tumor activity." (PMID 38918390, 2024). "Further experimental results indicate that the ADAM17 shedding heparin-binding epidermal growth factor (HB-EGF) and amphiregulin in tumour cells are molecular mediators of macrophage education." (PMID 38069391, 2023). "Only the CD16A isoform is able to activate tumor cell destruction, but CD16A is easily lost due to cleavage by ADAM17." (PMID 38068428, 2023). "H. pylori-induced chronic inflammation upregulates ADAM10 and ADAM17 expression, resulting in increased shedding of membrane-bound TNFRs or EGFR ligands, and is related to tumor proliferation and lower patient survival rates." (PMID 36572816, 2023). "In subcutaneous and orthotopic lung tumor models, ADAM17 inhibition by the novel ADAM17-specific therapeutic antibody MEDI3622 in combination with radiotherapy induced a strong anti-angiogenic effect and tumor shrinkage." (PMID 36998455, 2023).
tumor (continued). "Tumor infiltration by activated immune cells promote secretion of factors such as TGF-β1, TNF-α, and ADAM17 intensifying EMT signals and further driving EMT progression in the cancer cell population, resulting in tumor-promoting positive feedback loop." (PMID 38086828, 2023). "In summary, our study establishes ADAM17 as a crucial factor in HCC, influencing tumour development and patient outcomes." (PMID 38069391, 2023). "An example of utilizing miRNA targets is the attempt of enhancing the tumor-suppressing effect of miR-122, which targets ADAM10, IGF1R, as well as cyclin G1 and ADAM17." (PMID 37108330, 2023). "The pro-tumoral properties of ADAM17, VWF, and EDN1 have been well-studied in the literature, and targeted therapy has demonstrated the effects of tumor-inhibiting." (PMID 36902193, 2023). "Targeting a bottleneck like ADAM17 can affect the entire composition of the TME and tumor growth, angiogenesis, metastasis, and invasion." (PMID 36998455, 2023). "Moreover, drugs targeting ADAM17 from the DrugBank database showed eight small molecule compounds targeted only for ADAM17, demonstrating the therapeutic significance of targeting ADAM17 for both the prevention of tumor progression and SARS-CoV-2 attacking in immune implications." (PMID 35720350, 2022). "We found that the methylation status of the ADAM17 promoter in BLCA, THCA, and READ tumor tissues was significantly lower than correlated normal tissues." (PMID 36558177, 2022). "Another anti-ADAM17 monoclonal antibody, MEDI3622, inhibits tumor-dependent EGFR activity with IC50 values of 39 pmol/L and 132 pmol/L against human and murine ADAM17, respectively." (PMID 36466812, 2022). "In conclusion, we provide evidence that ADAM17 mediates a paracrine EGFR-ligand-chemokine feedback loop, whereby cancer cells hijack macrophages to promote tumor progression." (PMID 35998057, 2022). "The search terms “ectoprotease”, “cell surface protease”, “DPP4/CD26”, “FAP/Seprase”, “APN/CD13”, “ADAM17/TACE”, “MMP/gelatinase”, “drug”, “inhibitor”, “clinical trial”, “metabolism”, “tumour”, “microenvironment” were employed for this purpose." (PMID 35158891, 2022). "Taken together, these findings suggest a critical role of the ADAM17-EGFR (HB-EGF/AREG) axis in the polarization of TAMs, which also provides a new strategy for the anti-tumor immunotherapy." (PMID 36466812, 2022). "While excessive tumor-generated high-affinity EGFR ligands block target engagement by PEPDG278D, aderbasib, an inhibitor of ADAM10 and ADAM17, enables PEPDG278D to exert strong antitumor activity by inhibiting ligand shedding." (PMID 35650607, 2022). "In the study presented, we approached the expression of both ADAMs immunohistochemically and revealed a moderate to high ADAM17 and a distinctly weaker ADAM10 protein expression in RB patients’ tumor sections." (PMID 36293469, 2022). "Some double-negative feedback loops, including miR-143 (LIMK1, SOX2) and miR-145 (ADAM17, NEDD9, SOX2), also result in miR-143 and miR-145 downregulation in tumor cells." (PMID 35205713, 2022). "Together, our findings identify ADAM17-mediated EGFR ligand shedding as a potentially novel molecular mechanism, used by cancer cells to manipulate and hijack macrophages to support tumor progression." (PMID 35998057, 2022). "Future studies should focus on confirming tumor-derived exosomal ADAM17 as a plasma-based biomarker for the non-invasive screening of patients with CRC, as well as on the assessment of targeted ADAM17-based therapeutics against CRC liver metastasis." (PMID 34650435, 2021). "The metalloprotease, a disintegrin and metalloproteinase 17 (ADAM17), can activate ligands of the epidermal growth factor receptor (EGFR) and contribute to tumor progression." (PMID 34224305, 2021). "There was a clear correlation between ADAM17 and clinical parameters such as FIGO stage, and residual tumor burden after primary debulking." (PMID 34771725, 2021).